IL2RB (interleukin 2 receptor subunit beta)
Description:
Receptor for interleukin-2. This beta subunit is involved in receptor mediated endocytosis and transduces the mitogenic signals of IL2. Probably in association with IL15RA, involved in the stimulation of neutrophil phagocytosis by IL15.
Synonyms: CD122; IL15RB; IMD63; P70-75
Tractability: Small molecule: a structure with a bound ligand is known. Antibody: a drug acting on it is in phase 1 trials; UniProt places it where antibodies can reach, with high confidence; its Gene Ontology location is reachable by antibodies, with high confidence; UniProt predicts a signal peptide or a membrane-spanning region. PROTAC: its protein half-life has been measured. Other modalities: an approved drug acts on it.
Target class: Membrane receptor
Gene: Protein-coding gene on chromosome 22 (37,118,666 to 37,176,676, reverse strand). Ensembl gene ENSG00000100385.
Subcellular location: Cell membrane
Pathways (Reactome):
Immune System: Interleukin receptor SHC signaling; Interleukin-15 signaling; Interleukin-2 signaling
Signal Transduction: RAF/MAP kinase cascade
Gene Ontology:
Molecular function: coreceptor activity; interleukin-15 receptor activity; interleukin-2 binding; interleukin-2 receptor activity; protein binding; cytokine receptor activity
Biological process: cytokine-mediated signaling pathway; interleukin-15-mediated signaling pathway; interleukin-2-mediated signaling pathway; negative regulation of apoptotic process; positive regulation of phagocytosis; cell surface receptor signaling pathway via JAK-STAT; immunoglobulin mediated immune response; positive regulation of leukocyte differentiation; positive regulation of leukocyte proliferation; positive regulation of MAPK cascade; protein-containing complex assembly; signal transduction
Cellular component: cell surface; interleukin-15 receptor complex; interleukin-2 receptor complex; membrane; plasma membrane; cytosol; endosome; external side of plasma membrane
Genetic constraint (gnomAD): Loss-of-function variants: 14 observed, 35.76 expected, observed/expected ratio (o/e) 0.39, 90% interval 0.26 to 0.61. The upper end of that interval is the gene's LOEUF score, 0.61, which puts it in group 2 of 6, group 1 being the genes least tolerant of losing a copy. Missense variants: 608 observed, 646.83 expected, observed/expected ratio (o/e) 0.94, 90% interval 0.88 to 1. Synonymous variants: 282 observed, 284.1 expected, observed/expected ratio (o/e) 0.99, 90% interval 0.9 to 1.1.
Gene-disease validity (ClinGen):
ClinGen rates the evidence that IL2RB causes each of these diseases.
immunodeficiency 63 with lymphoproliferation and autoimmunity (autosomal recessive): Moderate.
Homologues: Orthologues: chimpanzee IL2RB (99% identical), macaque IL2RB (94% identical), dog IL2RB (70% identical), guinea pig IL2RB (61% identical), pig IL2RB (60% identical), rat Il2rb (58% identical), mouse Il2rb (57% identical), tropical clawed frog il2rb (25% identical), zebrafish il2rb (19% identical), zebrafish il21r.1 (13% identical), zebrafish csf2rb (13% identical). Paralogues in human: IL21R (19% identical), IL9R (18% identical), IL4R (16% identical), CSF2RB (15% identical), EPOR (13% identical), MPL (13% identical), IL7R (11% identical).
Diseases named in the same sentence as IL2RB in open-access papers:
IL2RB is named in the same sentence as 133 diseases in open-access papers, as found by Europe PMC text mining. Sharing a sentence is not in itself a finding about the gene and the disease. The quoted sentences say what the papers report.
Autoimmunity (26 papers, 2012 to 2026). The occurrence of an immune reaction against the organism's own cells or tissues. "Autosomal recessive mutations in IL2RB (in M5) have been recently characterized in severe autoimmunity and viral susceptibility, reflecting the important functions of IL2RB in T and natural killer cells signalling and in maintaining immune tolerance." (PMID 40656995, 2025). "IL2RB can alter gene expression and signal transduction in T and NK cells as a result of early-onset autoimmunity and immunodeficiency." (PMID 36118358, 2022). "IL-2 signaling also regulates immune tolerance, with Il2−/−, Il2ra−/−, and Il2rb−/− mice developing autoimmunity, while adoptive transfer of Treg cells into Il2rb−/− mice prevents autoimmunity, consistent with the nonredundant role of IL-2 in the development of Treg cells." (PMID 40680114, 2025). "Consequently, we analyzed Il2rb–/– mice before 6 weeks of age to avoid the potential skewing of iNKT cell differentiation due to autoimmunity." (PMID 34054809, 2021). "We aimed to investigate for the first time the potential influence of the IL2/IL21, IL2RA and IL2RB most associated polymorphisms with autoimmunity on the endogenous non-anterior uveitis genetic predisposition." (PMID 23676143, 2013).
autoimmune disease (19 papers, 2011 to 2025). A disorder resulting from loss of function or tissue destruction of an organ or multiple organs, arising from humoral or cellular immune responses of the individual to their own tissue constituents. "Subsequent studies observed that mice deficient in CD122, the IL2Rβ chain, developed autoimmune disease because they were devoid of functional Treg cells." (PMID 28163905, 2017). "IL2RB is well known to be a regulator of interleukin pathways and recently it has been reported that mutations in this gene result in susceptibility to EBV and CMV infections in addition to autoimmune disease." (PMID 35698050, 2022). "In addition, a series of studies have demonstrated that IL2RA and IL2RB participate in inflammatory processes in various human autoimmune diseases such as type I diabetes, rheumatoid arthritis (RA), and multiple sclerosis (MS)." (PMID 34485395, 2021). "Additionally, genetic associations between different polymorphisms located within the IL2/IL21 region as well as within both IL2RA and IL2RB loci and several autoimmune diseases have also been reported." (PMID 23676143, 2013). "We found that CD247, IL2RB and IL2 ranked 32th, 34th and 39th, respectively, and have been associated with RA in follow-up study of GWAS and studies exploring shared susceptibility loci among autoimmune diseases." (PMID 21980439, 2011). "Our results indicate that the analyzed IL2RA and IL2RB polymorphisms do not seem to play a significant role on the non-anterior uveitis genetic predisposition, similar to what has been reported in other autoimmune diseases such as inflammatory bowel disease and celiac disease." (PMID 23676143, 2013). "We found, for example, that Cluster 7 represents a set of genes annotated by terms related to autoimmune disease and pathogen response, and contains a number of genes that mediate tissue interactions with the immune system, including INFG, IL2, IL2RB, and FAS." (PMID 29176608, 2017). "The importance of γc cytokines to tTreg development is highlighted by the absence of this population from the thymus and periphery of IL-2R-γc knockout animals and spontaneous development of autoimmune diseases in mice lacking IL-2Rβ (CD122), which can be prevented by infusion of donor Tregs." (PMID 23818888, 2013).
asthma (14 papers, 2011 to 2024). "IL2RB constitutes one of the receptor subunits for IL-2 and IL-15 and dysregulated signalling of both of these immunoregulatory cytokines has been linked to asthma and allergy." (PMID 37794188, 2023). "IL2RB is currently associated to asthma and predicted to be associated also to eczema and rhinitis." (PMID 28598986, 2017). "Review of previous T1D genome-wide association results revealed that four (human leucocyte antigen (HLA), gasdermin B/ORM1 (Saccharomyces cerevisiae)-like/gasdermin B/, GSDMB/ORMDL3/GSDMA and IL2RB) of ten loci recently reported to be associated with asthma were associated with T1D (p≤0.005)." (PMID 22069270, 2011). "Another large-scale GWAS for asthma has identified six asthma-susceptible loci, including IL1RL1/IL18R1, SMAD3, ORMDL3/GSDM, IL-33, IL2RB, and HLA-DQ." (PMID 34946955, 2021). "This previous study identified genes on chromosomes 2 (IL1RL1/IL18R1), 6 (HLA-DQ), 9 (IL33), 15 (SMAD3), 17 (ORMDL3/GSDMB), and 22 (IL2RB) correlated with asthma." (PMID 32512817, 2020). "They observed associations with asthma, particularly childhood-onset asthma, at multiple loci (ORMDL3/GSDMB, IL1RL1/IL18R1, HLA-DQ, IL33, SMAD3, and IL2RB)." (PMID 23028483, 2012). "Among the asthma genes identified in genome wide association studies, ROBO1, RORA, HLA-DQB1, IL2RB and PDE10A were differentially expressed during human lung development." (PMID 21699702, 2011). "Our preliminary results confirm that three asthma susceptibility loci: 2q12.1 (IL1RL1), 6p21.32 (HLA-DQA1/B1/A2/B2), and 22q12.3 (IL2RB) each have VDR- and IKZF3-binding sites either in enhancers predicted by GeneHancer to target these genes or within these genes themselves." (PMID 38567749, 2024). "IL-6 is a cytokine that regulates cell growth and differentiation, immune response and its expression was related to metabolic dysfunction and asthma severity, IL-9 orchestrate inflammation that takes place in asthma while IL2RB is involved in T cell-mediated immune responses." (PMID 36143090, 2022). "Among the asthma genes identified in GWAS, ROBO1, RORA, HLA-DQB1, IL2RB and PDE10A showed most significant evidence of involvement in lung development (all adjusted p < 0.001 for differential expression)." (PMID 21699702, 2011). "Among the GWAS asthma genes, ROBO1, RORA, HLA-DQB1, IL2RB and PDE10A were differentially expressed in the human data." (PMID 21699702, 2011). "Among genes identified in asthma GWAS, ROBO1, RORA, HLA-DQB1, IL2RB and PDE10A showed most consistent expression patterns and from asthma candidate genes, e.g. NOD1, EDN1, CCL5 and HLA-G were identified." (PMID 21699702, 2011). "At the IL2RB locus (encoding the beta subunit of the interleukin-2 receptor), the minor allele (A) of rs228953 (MAF = 47%), associates with lower eosinophil count and less risk of asthma but the variant has not been reported to be in high LD with a coding variant." (PMID 37794188, 2023).
COVID-19 (14 papers, 2020 to 2025). A disease caused by infection with severe acute respiratory syndrome coronavirus 2. "After adjustment for confounding factors, seven proteins that were highly abundant and associated with an increased hazard of critical COVID-19 outcome were SLAMF1, CCL25, IL2RB, IL10RA, IL15RA, IL18 and CST5." (PMID 40475767, 2025). "Here, we demonstrated that the unique signature featuring SLAMF1, CCL25, IL2-RB, IL10RA, IL15RA, IL18, and CST significantly increased the risk of critical illness in COVID-19 patients." (PMID 40475767, 2025). "The respective APNet bipartite graph contained a large cluster (IL10RA, ACTN4, ITGB2, IL2RB, BIRC2, ITGAM, HMOX1, TIMP1) linked with established COVID-19 inflammatory and immune signalling cascades." (PMID 39921901, 2025). "Similarly, the expression of IL2RG (CD132) was significantly elevated in severe COVID-19 patients (p < 0.001), whereas IL2RB (CD122) expression remained largely unchanged across the groups." (PMID 41459501, 2025). "The IL2RB gene, for example, which encodes an IL-2 receptor (IL-2R) chain, emerged as one of the central genes in the PPI network formed by down-regulated COVID-19 gene, indicating that IL2RB may be an essential target for understanding the COVID-19 disease progression and lymphopenia." (PMID 38262689, 2024). "Levels of SLAMF1, CCL25, IL2RB, IL10RA, IL15RA, IL18 and CST5 were significantly upregulated in patients with critical COVID-19 illness compared to individuals negative for COVID-19." (PMID 40475767, 2025).
Sepsis (12 papers, 2020 to 2025). Sepsis is defined as life-threatening organ dysfunction caused by a dysregulated host response to infection. "Another study showed that targeting IL2RB can do some help to reduce acute lung injury caused by sepsis." (PMID 39654893, 2024). "In conclusion, downregulation of miR-497-5p reduced ALI caused by sepsis through targeting IL2RB, indicating the potential effect of miR-497-5p for improving ALI caused by sepsis." (PMID 33954185, 2021). "Targeting IL2RB can reduce acute lung injury caused by sepsis." (PMID 36199375, 2022). "Gene expression profiling and bioinformatics analysis have indicated that IL2RB is weakly expressed in sepsis, which indicates that IL2RB may be a potential diagnostic tool for sepsis." (PMID 35332254, 2022). "However, the role of IL2RB in the regulatory mechanism of ALI caused by sepsis is unclear." (PMID 33954185, 2021). "IL2RB is recognized as an indicator of sequential organ failure and is negatively correlated with sepsis mortality." (PMID 39654893, 2024). "In the GSE65682 dataset, CD3E (AUC:0.9509), HLA-DRA (AUC:0.974), IL2RB (AUC:0.9931), ITK (AUC:0.9727) and LAT (AUC:0.9575) showed good diagnostic efficiency in distinguishing sepsis patients from healthy controls." (PMID 38166628, 2024). "The regulatory mechanism of lncRNA PRKCQ-AS1 on IL2RB need to be further explored to elucidate its function roles in sepsis." (PMID 37488493, 2023). "In conclusion, miR-497-5p deficiency alleviated the deterioration of sepsis-induced apoptosis and inflammation by upregulating IL2RB, which provided the basis for enriching the potential therapy of sepsis and ALI induced by sepsis." (PMID 33954185, 2021). "By targeting upregulation of the IL2RB expression, low expression of miR-497-5p improved ALI caused by sepsis." (PMID 33954185, 2021). "The downregulation of miR-497-5p reduced sepsis-induced inflammatory cytokine production and apoptosis, while the downregulation of IL2RB attenuated this protective effect." (PMID 33954185, 2021). "It showed association with CD2, IL2RB, and IL7R in adult SIRS and KLRG1 and TGFBR3 in adult sepsis, among others." (PMID 32318053, 2020). "TBX21, GNLY, PRF1, and IL2RB represent the immune status in sepsis." (PMID 41139765, 2025). "For further investigating whether miR-497-5p/IL2RB affects sepsis-induced ALI in vitro, we firstly transfected BEAS-2B cells with si-IL2RB to knock down IL2RB expression." (PMID 33954185, 2021). "Furthermore, the hub genes TLR5, FCGR1A, ELANE, GNLY, IL2RB and TGFBR3, which may be associated with the prognosis of sepsis, and their negatively correlated microRNAs, were analysed." (PMID 35332254, 2022). "Hence, miR-497-5p/IL2RB was selected to validate its role in the alleviation of sepsis-induced ALI." (PMID 33954185, 2021). "As shown in these figures, the expression levels of RETN, S100A12, IL18R1, and KL were higher in the sepsis group, while that of GZMB, HLA-DPA1, CD3E, IL2RB, CD3G, and CCR3 were higher in the normal group (p < 0.05)." (PMID 38124071, 2023). "Our findings showed that the expression of RETN, S100A12, IL18R1, and KL was higher in the sepsis group, while the expression of GZMB, HLA-DPA1, CD3E, IL2RB, CD3G, and CCR3 was higher in the control group." (PMID 38124071, 2023). "In the two groups of different expression trend modules, the core genes such as CD160, GATA2, GNLY, IL2RB and TGFBR3 were downregulated in the sepsis group, while genes such as ELANE, IL1R1, TLR5, FCGR1A, MAPK14 and PCSK9 were upregulated." (PMID 35332254, 2022). "Additionally, five hub immune-related genes (CD3E, HLA-DRA, IL2RB, ITK and LAT) were identified from the protein–protein interaction network, and sepsis patients with higher expression of hub genes had a better prognosis." (PMID 38166628, 2024). "Consequently, the genes TLR5, FCGR1A, ELANE, GNLY, IL2RB and TGFBR3 genes were ultimately identified as hub genes in sepsis." (PMID 35332254, 2022).
Sepsis (continued). "Also, IL2RB was negatively correlated with Sequential Organ Failure Assessment (SOFA) and mortality of sepsis." (PMID 33954185, 2021).
melanoma (10 papers, 2017 to 2026). A malignant, usually aggressive tumor composed of atypical, neoplastic melanocytes. "The NK cell/Anti-PD-1 signature devised in melanoma models also strongly correlated with IL2RB (R = 0.77, P < 0.0001 and R = 0.77, P < 0.0001) as did the pembrolizumab signature from the KEYNOTE-001 phase I clinical trial (R = 0.88, P < 0.0001 and R = 0.84, P < 0.0001)." (PMID 33928242, 2021). "Using the Human Protein Atlas, we identified an IL2RB IHC antibody which stains small populations of immune cells in many tumor types including CRC, melanoma, breast, lung, pancreatic and head and neck." (PMID 33928242, 2021).
colitis (7 papers, 2014 to 2024). Inflammation of the colon. "A significant up-regulation of genes encoding the following cytokines and their receptors—Il13, Il16, Il27, Il2rb, Il2rg, Il6r Il10ra, Faslg, Ltb, Osm, Spp1, Tnf, Tnfsf14—was noted in animals with colitis (CβG−)." (PMID 31590413, 2019).
colorectal cancer (6 papers, 2017 to 2024). A primary or metastatic malignant neoplasm that affects the colon or rectum. "In several tumor types, IL2RB could be used as a potential predictive biomarker of therapy with ICi, particularly in colorectal cancer." (PMID 38790160, 2024). "Furthermore, by studying the evolutionary genetic algorithms, Alderdice and colleagues found that IL2RB is a potential predictive biomarker of immune checkpoint therapy for colorectal cancer, which is consistent with our study." (PMID 36518255, 2022).
leukemia (6 papers, 2015 to 2023). A malignant (clonal) hematologic disorder, involving hematopoietic stem cells and characterized by the presence of primitive or atypical myeloid or lymphoid cells in the bone marrow and the blood. "The results showed that the expression of IL-2RG and IL-2RB mRNAs was decreased until reaching an undetectable level at 48 and 72 hours posttransduction, respectively, in K562-WT1-siRNA-GFP+ (WT1-siRNA) leukemia cells." (PMID 33110919, 2020).
lymphopenia (6 papers, 2013 to 2025). Reduction in the number of lymphocytes. "At month three, LC patients had elevated IL10RB and MCP-1, whereas by month six, levels of several proteins (monocyte chemoattractant proteins MCP2/CCL8 and MCP4/CCL13, lymphopenia associated IL2RB, and TGF-signaling LAP/TGFb1) had fallen." (PMID 40572685, 2025).
viral infection (6 papers, 2011 to 2025). "The Human T-cell Leukemia Virus 1 Infection pathway involved genes such as STAT5A and IL2RB, highlighting a heightened immune response against viral infections." (PMID 40621499, 2025). "Apart from this similarity, different virus infection pathways owned their unique genes, with STAT1,RSAD2 and IRF9 in the influenza A pathway,IL-2RA,IL-2RB and CD40 in the HTLV-1 infection pathway, HCFC1, MAP3K7, SOCS3, IRF9, HMGN1, and FAS in the herpes simplex infection pathway." (PMID 35795668, 2022).
breast carcinoma (5 papers, 2019 to 2021). "In addition, AKT3 was targeted by miR-29 in breast cancer, and cytokine receptor (IL2RB and IL6R) and one component of the PI3K complex (PIK3R3) were also targeted by miR-34a and miR-29, respectively, in DLBCL." (PMID 30820547, 2019). "Furthermore, the other three hub genes, IL2RB, XCR1 and CXCR6, have been reported to be related with the prognosis of other cancers, such as early breast cancer, salivary adenoid cystic carcinoma, bladder and hepatocellular cancers." (PMID 33719152, 2021). "Risk score also predicted expression of several immune checkpoints, including PD1, PDL1, PDL2, TIM3, CD28, ICOS, IL2RB, and 41BB, in TNBC patients, and its predictive value in these patients was similar to that observed in the overall breast cancer patient cohort." (PMID 32756008, 2020).